MB (myoglobin)
Diseases named in the same sentence as MB in open-access papers (continued):
Sharing a sentence is not in itself a finding about the gene and the disease.
myocarditis (14 papers, 2016 to 2026). Myocarditis is a condition that is characterized by inflammation of the heart muscle (myocardium). "For predicting the occurrence of ICI-associated myocarditis, a baseline model incorporating elevated eosinophil ratio, reduced lymphocyte ratio, and elevated myoglobin demonstrated an area under the ROC curve (AUC) of 0.699 (95% CI, 0.626-0.772, P < 0.001)." (PMID 41988173, 2026). "While elevated myoglobin levels detected myocarditis in mice with 70% accuracy, diagnostic accuracy for TnT-hs was only 43%." (PMID 32006209, 2020). "Since myocarditis typically presents as a systemic illness that may also affect skeletal muscle, it is plausible that more severe acute myocarditis may be associated with the release of myoglobin from skeletal muscle, which could contribute to higher blood levels of the marker." (PMID 32006209, 2020). "Myoglobin was found to be significantly increased in men with myocarditis compared to women (p = 0.04)." (PMID 36937911, 2023). "Recently, sera myoglobin levels were found to be a strong predictor of acute myocarditis based on cardiac MRI and this sera biomarker was also detected in a viral model of myocarditis." (PMID 36937911, 2023). "Similar to the human cohort, we performed ROC analysis in data obtained from mice to determine accuracy of myoglobin and TnT-hs for detecting acute myocarditis." (PMID 32006209, 2020). "Our findings on myoglobin obtained from the human myocarditis cohort reproduced in a clinically relevant mouse model of CVB3 myocarditis." (PMID 32006209, 2020). "Mean baseline levels of myoglobin at symptom onset were 77 ± 75 μg/L in myocarditis vs. 24 ± 14 μg/L in controls (p = 0.03)." (PMID 32006209, 2020). "Similar to findings in the human cohort, average myoglobin levels were higher in mice with myocarditis (1468.8 ng/mL) vs. controls (1032.3 ng/L; p = 0.02)." (PMID 32006209, 2020). "Receiver operating curve (ROC) analysis determined myoglobin ≥ 87 μg/L as cutoff to identify myocarditis (92% sensitivity, 80% specificity)." (PMID 32006209, 2020). "Among 44 patients with myocarditis, there were 18 patients in whom both levels of myoglobin as well as TnT-hs were elevated." (PMID 32006209, 2020). "As we found a strong correlation between myoglobin and LGE, we sought to determine the optimal cutoff for serum myoglobin to detect acute myocarditis on CMR." (PMID 32006209, 2020). "This is the first study to demonstrate a strong correlation of myoglobin with LGE on CMR in patients with acute myocarditis and to suggest a robust cutoff value for myoglobin to predict LGE on CMR." (PMID 32006209, 2020). "A cutoff value of 87 μg/L for myoglobin performed with 92% sensitivity, 80% specificity, and 85% accuracy in identifying patients with myocarditis and LGE on CMR." (PMID 32006209, 2020). "Using the cutoff for myoglobin of 1139.2 ng/mL resulted in 70% accuracy for the detection of myocarditis, AUC = 0.68, 65% sensitivity, and 80% specificity." (PMID 32006209, 2020). "A time course analysis of cardiac and inflammatory markers in myocarditis revealed peak of myoglobin levels upon admission and normalization 3 h later." (PMID 32006209, 2020). "The data are biologically plausible, as myoglobin is released during cardiac injury and its expression on EMBs increases with the severity of myocarditis." (PMID 32006209, 2020). "Therefore, it is critical that myoglobin serum levels are determined early in patients with suspected myocarditis." (PMID 32006209, 2020). "Horike and colleagues analyzed the degree of myoglobin staining in EMBs of patients with myocarditis using immunohistochemistry and found that myoglobin staining relates to disease severity as well as the duration of acute myocarditis." (PMID 32006209, 2020). "Importantly, we tested the newly developed cutoff for serum myoglobin with TnT-hs, the current laboratory gold standard for the diagnosis of myocarditis." (PMID 32006209, 2020).
myocarditis (continued). "Mean myoglobin levels were 77 ± 75 μg/L in myocarditis and 24 ± 14 μg/L in controls (p = 0.03)." (PMID 32006209, 2020). "Furthermore, the ability to obtain results within 1 h makes myoglobin an excellent screening tool for myocarditis." (PMID 32006209, 2020). "However, TnT-hs and myoglobin levels were higher in patients with myocarditis compared to controls." (PMID 32006209, 2020). "We show for the first time that serum myoglobin strongly correlates with LGE on CMR in acute myocarditis and that myoglobin may serve as a surrogate for severe myocardial damage in patients with myocarditis." (PMID 32006209, 2020). "Markers of myocardial damage such as myocardial muscle creatine kinase, myoglobin and troponins may be useful, but do not represent an unequivocal identification of myocarditis, nor pericarditis." (PMID 27931201, 2016). "Patients who present with dyspnea, chest pain, muscle aches, or generalized weakness should be evaluated thoroughly using CK, myoglobin, Troponin I, ECG, and TTE to rule out ischemic heart disease and evaluate for myocarditis." (PMID 31417814, 2019). "Surprisingly, correlation of TnT-hs and CK with LGE were only weak for patients with myocarditis in this study, but aligns with a recently published study analyzing the correlation of LGE with TnT-hs and CK, but not with myoglobin in patients with suspected myocarditis." (PMID 32006209, 2020).
Myalgia (13 papers, 2018 to 2025). "Both CK and myoglobin levels were elevated, and the patient experienced generalized myalgia and fatigue." (PMID 40635153, 2025). "A 15-year-old Chinese boy presented with myalgia after strenuous exercise, accompanied by transient increases in serum creatine kinase and myoglobin and persistent hyperuricaemia and hyperbilirubinaemia." (PMID 33514355, 2021). "The most commonly reported clinical features in this outbreak were myalgia and muscle weakness, as well as abnormal levels of myoglobin and CK." (PMID 33219647, 2020). "Metabolic myopathies present with either permanent (fixed) or episodic abnormalities, such as weakness, wasting, exercise-intolerance, myalgia, or an increase of muscle breakdown products (creatine-kinase, myoglobin) during exercise." (PMID 32316520, 2020). "The patient was diagnosed with Hepatitis B envelope Antigen positive CHB, cirrhosis, LA and RM characterized by myalgia and elevated myoglobin." (PMID 29625557, 2018). "We not only regularly tested urinary hemoglobinuria, but also serum CK-MB and myoglobin in the mice at the end of the experiment, and ruled out that the mice had statin-associated muscle pain (myalgia) and needed to be stopped early." (PMID 36693830, 2023). "Upon presentation, the patient complained of intense myalgia which wasn't supported objectively by musculoskeletal deficit, nevertheless, his renal function was impaired coupled with very high levels of creatinine phosphokinase (CPK) and myoglobin levels." (PMID 37207082, 2023).
acute coronary syndrome (12 papers, 2012 to 2023). Signs and symptoms related to acute ischemia of the myocardium secondary to coronary artery disease. "Thus, if myoglobin is added as a biomarker for the identification of acute coronary syndrome, the diagnostic workflow may be executed more quickly and accurately." (PMID 27717317, 2016). "Myoglobin (Mb) is one of the most reliable markers for predicting future cardiovascular events and/or diagnosing patients with acute coronary syndrome." (PMID 37426287, 2023). "Takotsubo cardiomyopathy has already cardiac biomarkers, such as the NT-proBNP (N-terminal B-type natriuretic peptide)/myoglobin and NT-proBNP/troponin T ratios for the diagnosis of acute coronary syndromes and stress-induced cardiomyopathy." (PMID 35514439, 2022). "While myoglobin and CK had been used to diagnose acute coronary syndrome (ACS) in the past, cardiac troponin is now the standard of care during the last decade due its higher specificity." (PMID 32006209, 2020). "It was previously reported that elevated myoglobin was a predictive biomarker better than cTnI for 5-year mortality in patients evaluated in the emergency department for possible acute coronary syndromes (ACS)." (PMID 32903533, 2020). "Various combinations of creatine kinase‐MB, myoglobin, and cardiac troponin I or T (cTnI/cTnT) have been used to evaluate patients with suspected acute coronary syndromes." (PMID 28939707, 2017). "The three methodologies were also applied to an acute coronary syndrome dataset in which serum myoglobin levels were used as a biomarker for detecting acute coronary syndrome." (PMID 22844346, 2012). "In addition, some authors have reported that IMA was found to be a more sensitive indicator than TnI, myoglobin, and CK-MB in acute coronary syndrome, because IMA levels can rise within 30 min and then continue to increase for the next 6–12 h." (PMID 36611075, 2023). "Myoglobin, a hemoprotein expressed in the cytoplasm of striated muscle cells (cardiac and skeletal muscle), has long been used as a biomarker in the early detection of acute coronary syndrome due to its rapid release into circulation (within the first 30 min)." (PMID 36012430, 2022). "Several studies have shown that the use of MCB tests—such as troponin I, CK-MB, and myoglobin, which are related to cardiomyocyte necrosis, or BNP, which is related to cardiomyocyte function—can effectively improve the risk classification of patients with acute coronary syndrome." (PMID 27717317, 2016). "As compared to non‐acute coronary syndromes (ACS) patients, ACS patients have lower BMI, sodium, albumin (ALB), and higher RBC, WBC, BPC, neutrophil (%), NT‐proBNP, hs‐cTnI, myoglobin, CK‐MB, TB, LDL‐C, AST, and CK." (PMID 37323876, 2023). "The following markers for acute coronary syndrome are FDA-approved: creatin kinase, myoglobin and cardiac troponin." (PMID 25417001, 2014).
breast carcinoma (11 papers, 2006 to 2023). "The expression of myoglobin (MB), well known as the oxygen storage and transport protein of myocytes, is a novel hallmark of the luminal subtype in breast cancer patients and correlates with better prognosis." (PMID 36232784, 2022). "The low-level expression of MB protein in the mammary gland is clinically relevant as its expression in mammary carcinoma correlates with a higher degree of cell differentiation in the luminal subtype of cancer." (PMID 37161046, 2023). "Here we report that, even at this low expression level, MB efficiently regulates fatty acid (FA) turnover, trafficking and composition in breast epithelia, at in vivo (milk) and in vitro (breast cancer cells) levels." (PMID 36223378, 2022). "Myoglobin mRNA was also detectable in breast cancer cell lines, in a small subset, even at surprisingly high levels." (PMID 20531416, 2010). "Myoglobin (MB) is expressed in different cancer types and may act as a tumor suppressor in breast cancer." (PMID 37161046, 2023). "Although the level of MB protein expression is 350 times higher in human breast cancer samples than in matching normal breast tissues, MB expression level is far lower in breast epithelia than muscle cells, suggesting that MB fulfils functions other than the classic O2 binding and transportation." (PMID 36223378, 2022). "Based on our data, myoglobin therefore might influence the survival of breast cancer cells, possibly due to its ROS and NO scavenging properties and could be a valuable target for cancer therapy." (PMID 34671319, 2021). "Although precise mechanisms need to be further elucidated, our data indicate that myoglobin plays an important role in survival of breast cancer cells, possibly due to its ROS and NO scavenging properties and might be a valuable target for cancer therapy." (PMID 34671319, 2021). "Blood samples were collected from 152 breast cancer patients before and after each cycle of doxorubicin chemotherapy to measure the serum levels of ischemia-modified albumin, cardiac troponin T and creatine kinase-MB." (PMID 24223946, 2013). "Thus, our data indicate that myoglobin might influence the survival of breast cancer cells, possibly due to its ROS and NO scavenging properties and could be a valuable target for cancer therapy." (PMID 34671319, 2021). "Data obtained for 130 HER2-positive breast cancer patients do not support an influence of N-terminal brain natriuretic peptide (NT-proBNP), creatine kinase-MB (CK-MB), or myoglobin on the frequency of TIC." (PMID 35884413, 2022). "We aimed to clarify the incidence and the clinicopathological value of non-muscle myoglobin (Mb) in a large cohort of non-invasive and invasive breast cancer cases." (PMID 20531416, 2010).
chronic kidney disease (11 papers, 2020 to 2025). Impairment of the renal function secondary to chronic kidney damage persisting for three or more months. "In another study, elevated serum myoglobin level was associated with advanced chronic kidney disease." (PMID 38036859, 2024). "Other predisposing factors that can aggravate the toxicity of myoglobin are older age, frailty, multisystem diseases, impaired liver function, and impaired kidney function (such as chronic kidney disease)." (PMID 36779111, 2023). "Although myoglobin has not been put forward as a DKD biomarker, plasma levels of myoglobin have been associated with chronic kidney disease, and higher levels of myoglobin with higher stages of chronic kidney disease." (PMID 31805809, 2020). "We accepted that chronic mild rhabdomyolysis was the cause of the chronic kidney disease (high levels of creatinine and uric acid), which is not glomerular but instead tubulointerstitial due to the reabsorption of myoglobin by the renal tubules." (PMID 40429823, 2025). "In other patients, timely reduction of myoglobin levels could potentially help preserve renal function and prevent progression to end-stage renal disease, highlighting the importance of early and aggressive myoglobin removal in similar clinical scenarios." (PMID 39872682, 2025). "Binary logistic regression identified five critical determinants regarding poor renal recovery, including chronic kidney disease (CKD) history, renal hypoperfusion, circulation arrest time, intraoperative urine, and myoglobin." (PMID 38707890, 2024).
myositis (11 papers, 2012 to 2025). "Following the initiation of myositis treatment, CK and MB levels declined, indicating a positive treatment response, whereas cTnT levels exhibited a delayed peak and slower decline." (PMID 40626321, 2025). "All patients with elevated levels of muscle damage markers belong to the PTLDS group; in the control group, the results for CK and myoglobin in both myositis antibodies positive patients were within the physiological range." (PMID 36836887, 2023). "Circulating creatine kinase, aldolase, and myoglobin are indicators of skeletal muscle damage, but these parameters are generally only measured in the clinical setting if a patient complains of muscle pain or the physician suspects myositis." (PMID 32218224, 2020). "Importantly, we found that serum resistin levels were strongly associated with CRP and global disease activity, and a trend was also observed towards correlation between resistin levels and myoglobin in patients with myositis-specific anti-Jo-1 antibody in contrast to anti-Jo-1 negative patients." (PMID 22577940, 2012). "Finally, elevated aminotransferases could also originate from myositis rather than liver injury, since myoglobin, hs-Troponin, and LDH values were higher in the non-survivors group." (PMID 36143014, 2022). "She had elevated levels of creatine kinase (CK), cardiac troponin I, and myoglobin (MYO), but MG and myositis-specific and myositis-related antibodies were negative." (PMID 36457566, 2022).
Obesity (11 papers, 2014 to 2024). Accumulation of substantial excess body fat. "Notably, we observed a significant reduction in SC AT MB expression (p = 1.69 × 10−4) after weight loss which may indicate a reversal of the obesity‐driven MB expression after weight loss in SC AT." (PMID 36480426, 2022). "Human transcriptome data indicate that the MB expression in WAT is regulated differently in obesity and correlates with UCP1 and other markers of adipose tissue browning, suggesting the functional significance of MB expression in human adipose tissue." (PMID 37759463, 2023). "In 3056 SC and VIS AT samples, we found differential MB expression with respect to the AT depots and the obesity state." (PMID 36480426, 2022). "In relation to this mechanism, several studies have indicated that patients with obesity may possess increased muscle mass, resulting in elevated levels of myoglobin and creatine kinase (CK) release following injury." (PMID 39803123, 2024). "Because human SGBS adipocytes showed an induction of MB expression during differentiation, we finally analyzed MB expression in human WAT to address the clinical relevance of our data and potential association with parameters of obesity and/or AT browning in humans." (PMID 36480426, 2022). "There are several explanations regarding the cause of ID in children with obesity, for example, inadequate iron intake, higher iron requirement due to higher body mass or blood volume, and lower myoglobin in the muscle due to a lack of physical activity." (PMID 34258058, 2021). "In lean patients, MB expression was significantly lower in SC AT compared to VIS AT, whereas the opposite was found in patients with obesity." (PMID 36480426, 2022). "We have here investigated for the first time MB expression in human VIS and SC white AT samples from well‐phenotyped individuals of the large Leipzig obesity biobank." (PMID 36480426, 2022). "In conclusion, we report for the first time that human MB is differentially expressed in SC and VIS AT depots, differentially regulated by the state of obesity, normalized after bariatric surgery and higher expressed in AT samples that exhibit a higher thermogenic potential." (PMID 36480426, 2022).
Arrhythmia (9 papers, 2009 to 2026). Any cardiac rhythm other than the normal sinus rhythm. "CO has high affinity for myoglobin and binding to cardiac myoglobin can cause myocardial depression, hypotension and arrhythmias." (PMID 29506505, 2018). "The underlying mechanism of crush syndrome involves a rapid elevation in myoglobin and potassium levels, leading to nephrotoxic effects and cardiac arrhythmias." (PMID 37854473, 2023). "Although both myoglobin and troponin I were elevated in all SCD cases, the small sample sizes, particularly in the aortic dissection (n = 1) and arrhythmia (n = 3) groups, limit the interpretability of these findings." (PMID 39857776, 2025).
Hyperbilirubinemia (9 papers, 2013 to 2025). An increased amount of bilirubin in the blood. "Therefore, exercise can cause transient unconjugated hyperbilirubinemia due to myoglobin and hemoglobin breakdown, with a small additional contribution of conjugated hyperbilirubinemia due to its impact on liver blood flow." (PMID 39445286, 2024). "However, NIRS is limited in its relatively low diagnostic accuracy, specifically in cases of hyperbilirubinemia or elevated levels of myoglobin." (PMID 38082052, 2023). "Hyperbilirubinemia, medical conditions with an excess of specific proteins (myoglobin, heme, monoclonal gammopathies, others), and specific drugs can affect PCR assay; however, these were not present in our cases." (PMID 37519543, 2023). "The boy had hyperbilirubinaemia and hyperuricaemia since the age of 14 because of high-intensity long jump training, while CK and myoglobin levels were normal in between episodes." (PMID 33514355, 2021). "Orange urine has been attributed to hemoglobin, myoglobin, porphyria, methemoglobinemia, iron (hemochromatosis), beetroot pigment, rifampicin and conjugated hyperbilirubinemia." (PMID 23762661, 2013).